KLK3 (kallikrein related peptidase 3)
Diseases named in the same sentence as KLK3 in open-access papers (continued):
Sharing a sentence is not in itself a finding about the gene and the disease.
chromophobe renal cell carcinoma (1 paper, 2018). Chromophobe renal cell carcinoma is a rare subtype of renal cell carcinoma, originating from the intercalating cells of the collecting ducts and macroscopically manifesting as a well-circumscribed, highly lobulated, solid tumor that is usually diagnosed at an early stage. "Chromophobe renal cell carcinoma also had 4 up-regulated KLKs with excellent diagnostic power (KLK2: 0.990, KLK3: 0.974, KLK4: 0.989, KLK15: 0.97)." (PMID 29707153, 2018). "Our analysis differed and found that KLK1, KLK2, KLK3, KLK4 and KLK15 are highly upregulated in chromophobe renal cell carcinoma." (PMID 29707153, 2018). "Chromophobe renal cell carcinoma had increased expression of the following KLKs: KLK1 (32-fold), KLK2 (12-fold), KLK3 (69-fold), KLK4 (234-fold), KLK15 (132-fold), whereas decreased expression of KLK5 (5-fold), KLK6 (13-fold), and KLK7 (26-fold)." (PMID 29707153, 2018). "We identified four viable cancer biomarkers (KLK2, KLK3, KLK4 and KLK15) for chromophobe renal cell carcinoma with almost perfect sensitivity and specificity (AUC values: 0.97–0.99)." (PMID 29707153, 2018).
dementia (1 paper, 2025). Loss of intellectual abilities interfering with an individual's social and occupational functions. "Top proteins with high feature importance in the clinical impairment signature again highlighted ACHE and NPTXR as well as additional targets linked to neuroplasticity (EPHA4 and CNTFR) and immune activation (MSMP and KLK3), underscoring their potential for transdiagnostic dementia staging." (PMID 40665048, 2025).
Hyperinsulinemia (1 paper, 2021). An increased concentration of insulin in the blood. "Metformin and hyperinsulinemia changed the expression of extracellular proteins (e.g. metformin: CTSL, EGFR, IL5, KLK3; insulin: IL4, IL15, PGC, SORL1)." (PMID 33690729, 2021).
lupus nephritis (1 paper, 2024). Glomerulonephritis in the context of systemic lupus erythematosus. "For example, genetic variants in genes expressed in the kidney (including TNFRSF1B, KLK1, KLK3, ACE, AGT, and APOL1) may result in increased susceptibility to kidney injury and, as a result, in progression to lupus nephritis." (PMID 39124752, 2024).
urinary system cancer (1 paper, 2014). "Indeed, EGF/EGFR, FGFR2, KLK3, and PDGFRB were reported to play important roles in urinary system cancer development and progression." (PMID 24801713, 2014).
tumor (809 papers, 1997 to 2026). "Studies supporting an association of KLK3 with metastasis have mostly been performed in vitro, focusing on the proteolytic degradation of the extracellular matrix facilitating tumor cell invasion." (PMID 34948344, 2021). "Only one epithelial-associated gene (CLDN4) was more highly expressed in CTCs compared to tumours, and one epithelial-associated gene (KLK3) was expressed at lower levels." (PMID 34206049, 2021). "There was higher expression of 11 mesenchymal- and 5 epithelial-associated genes, and lower expression of one epithelial-associated gene (KLK3) in the CTCs compared to tumours, suggesting a hybrid-like phenotype." (PMID 34206049, 2021). "In the context of epithelial-associated differentiation, KLK3 was found to be downregulated in the CTCs compared to primary tumours in all four models, and CD24 was downregulated in BM18 and LuCaP105." (PMID 34206049, 2021). "Each tumor was found to exhibit high levels of transcripts encoding the AR and AR-regulated genes such as KLK3/PSA and TMPRSS2, indicating an active AR transcriptional program, an important clinical finding for prioritizing therapeutic options." (PMID 27167109, 2016). "However, the potential of KLK3 to stimulate tumor-associated angiogenesis and lymphangiogenesis via VEGF-C and VEGF-D activation does provide another possible mechanism by which KLK3 may support metastatic dissemination of cancer cells." (PMID 34948344, 2021). "Interestingly, KLK3 is a tumor-associated biomarker well known as prostate specific antigen (PSA)." (PMID 27825132, 2016). "While its diagnostic utility is clinically validated, emerging evidences reveal that KLK3 mRNA detection in whole blood has a predictive role in tumor progression and therapeutic resistance, which is expected to become a potential prognostic marker for PCa." (PMID 41247789, 2025). "KLK3’s canonical role as a serine protease involves cleaving extracellular matrix components and activating matrix metalloproteinases to promote tumor invasion and metastasis." (PMID 41247789, 2025). "Expression of prostate epithelial cell marker KLK3 was below detection in most tumours from castrated mice (62%, 23/37 mice), consistent with its known up-regulation by androgens." (PMID 35493092, 2022). "Some well-known secreted tumor markers include AFP, cell surface-associated protein (MUC1 or CA15-3), gastrin-releasing peptide, and prostate-specific antigen (or KLK3)." (PMID 35719915, 2022). "A functional analysis of tumor-associated proteins revealed the reduced expression of several proteinases, including dipeptidyl peptidase 4 (DPP4), carboxypeptidase E (CPE) and prostate specific antigen (KLK3), particularly in AG and metastatic PCa." (PMID 34556748, 2021). "Decreased levels of kallikrein-related peptidase 3 (KLK3) mRNA (which encodes prostate-specific antigen; PSA) were observed in CTC samples from all four models compared to their primary tumours." (PMID 34206049, 2021). "In contrast, both prostate-related (AR and KLK3) and tumor-derived (PCA3 and PSMA) genes were successfully detected in 780 LNCaP or 22Rv1 and 78 22Rv1 cells." (PMID 34771706, 2021). "Further, tumor-derived platelets biomarkers, as KLK3, FOLH1, and NPY, enable prediction after abiraterone therapy in castration resistant prostate cancer (CRPC) and KLK2, KLK3, and FOLH1 were associated with short OS." (PMID 33673461, 2021). "Despite being often detected in CTCs across all our PDXs (BM18: 6/11, LuCaP70: 8/11, LuCaP96: 7/10, LuCaP105: 9/10), lower levels of KLK3 were consistently observed in CTC samples compared to primary tumours." (PMID 34206049, 2021). "These and other proposed functions of KLK3 that promote or inhibit tumor growth and metastasis have been reviewed elsewhere." (PMID 34948344, 2021).
tumor (continued). "A functional analysis of tumor-associated proteins revealed reduced expressions of several proteinases, including dipeptidyl peptidase 4 (DPP4), carboxypeptidase E (CPE) and prostate specific antigen (KLK3) in AG and metastatic PCa." (PMID 34556748, 2021). "Earlier studies have shown that as tumour cells become more aggressive and motile, they reduce/lose expression of KLK3 at the level of single cells." (PMID 34206049, 2021). "We foresee that the modern three-dimensional tumor angiogenesis models would be useful for the elucidation of the role of KLK3 in tumor angiogenesis." (PMID 34948344, 2021). "CTCs were characterized by mRNA in situ padlock probe analysis which visualizes AR-V7, AR full length (AR-FL), and kallikrein-related peptidase 3 (KLK3, often referred to as prostate specific antigen (PSA)) transcripts directly in tumor cells." (PMID 32796730, 2020). "(D) qRT-PCR analysis of DECR1 and androgen regulated genes KLK2 and KLK3 mRNA expression in a cohort of 10 patient-derived human prostatic ex vivo tumor explants treated with enzalutamide (ENZ, 10 μM)." (PMID 32686647, 2020). "The involvement of KLK3/PSA for tumor progression is still debated with studies arguing both in favor or against a tumor-promoting function of KLK3." (PMID 31099754, 2019). "The gene KLK3 encodes the glyco-protein enzyme known as prostate-specific antigen (PSA), an important tumor marker used for diagnosis of prostate cancer in clinical practices." (PMID 30367578, 2018). "Semi quantitative PCR confirmed higher expressions of AR and KLK3 genes in tumor tissues compared to that in the BPH sample, which was considered as a reference control in the microarray experiment." (PMID 28852180, 2017). "When gene expression in high grade cancers was compared to that of low grade tumours, the expression of 20 of 25 genes tested were lower in higher grade tumours, and reached statistical significance for twelve, including KLK3 and MYBPC1." (PMID 27120785, 2016). "The use of kallikreins to track tumour burden has previously been documented in the clinic, most notably with KLK3 (PSA) in prostate cancer." (PMID 22102857, 2011). "BEX1 and FBLN were associated with ER, while FBLN1, HBEGF, KLK3, and TMPRSS2 were associated with tumor aggressiveness." (PMID 21134280, 2010). "In addition, tumor-derived exosomes enriched with KLK3 (prostate-specific antigen) or interleukin-8 contribute to the suppression of T-cell cytotoxicity through mechanisms involving metabolic reprogramming and direct inhibitory signaling." (PMID 40227610, 2025). "This hypothesis was confirmed through subsequent experiments, which demonstrated that T cells expressing KLK3 contribute to the establishment of a pre-metastatic niche for tumor cells." (PMID 37746302, 2023). "These KLK3-high T-cell clusters exhibit specific modules associated with extracellular vesicles (EVs) and exosomes, suggesting that the abundance of KLK3 might be attributed to EVs derived from tumor cells." (PMID 37746302, 2023). "In addition to its role in regulating tumor cell invasion and proliferation, ERG also plays an important role in negatively regulating tumor cell differentiation by inhibiting the transcription of genes such as KLK3/PSA and SLC45A3/Prostein." (PMID 35563163, 2022). "These SNPs might be one example of a causal SNP that could indirectly promote cancer progression by altering KLK3 isoform expression, which can impact the tumor microenvironment." (PMID 36293264, 2022). "Thus, the KLK3 eRNAs levels were indicated to be dissimilar in distinct tumor specimens and, furthermore, varied between normal and cancerous parts from the same tissue specimens." (PMID 36287118, 2022). "Therefore, it is not surprising that, using other models, apparently opposite effects for KLK3 have also been proposed, i.e., the promotion of tumor angiogenesis via the activation of VEGF-C and VEGF-D." (PMID 34948344, 2021).
tumor (continued). "However, downregulation of KLK3 in comparison with their primary tumours was observed, consistent with our findings in all PDXs examined." (PMID 34206049, 2021). "PSA (KLK3) plays a vital role in both normal biology and tumor growth and progression." (PMID 33150763, 2020). "For example, we found variable intensity of KLK3 staining in tumor cells with comparable levels of AR staining (lined boxes) and, conversely, variable intensity of AR staining in tumor cells with similar KLK3 staining (dotted circles)." (PMID 30644358, 2019). "The possible involvement of cathepsin D and KLK3 in tumor metastasis could be addressed in the appropriate gene-targeted mouse models." (PMID 31099754, 2019). "PSA (KLK3) is encoded by an androgen-dependent gene, and increased expression of PSA in an environment of castrate levels of circulating androgens indicates that adaptive androgen signaling has emerged in the tumor." (PMID 28134791, 2017). "This could be due to generally low KLK3 expression in tumours in response to castration." (PMID 35493092, 2022). "KLK3 expression is primarily regulated by the androgen receptor, and it is a commonly used readout of the level of receptor activation both clinically and experimentally, and the most facile explanation is therefore that androgen receptor signalling is downregulated in more aggressive tumours." (PMID 27120785, 2016). "Co-expression with known tumor markers (e.g., KLK3, MMP9) reinforces DOCK3’s tumor-specific expression signature." (PMID 41200217, 2025). "Factor 5 exhibits the highest signal in tumour regions, encompassing both Gleason 3 and Gleason 4 areas, accompanied by high expression of KLK2 and KLK3, which are markers of prostate glandular epithelium." (PMID 40167331, 2025). "Furthermore, we performed subcluster localization of the risk model with 6 genes in 2 TAN subclusters (Neu_c09_HLA and Neu_c07_KLK3), and the results revealed that these two subclusters may promote tumor progression through dysregulation of hypoxia and the phosphatidylinositol signaling system." (PMID 40901472, 2025). "For example, cancer RNA biomarkers such as KRAS, PCA3, PIK3CA mutants, EGFRvIII, FOLH1, KLK2, KLK3, EML4-ALK, and NYP have been reported to be sequestered by platelets that actively uptake tumor-derived material." (PMID 39274207, 2024). "In transcriptomic data from 138 CRPC tumours, levels of ST3GAL1 gene expression were negatively correlated with AR, KLK3, NKX3." (PMID 38448753, 2024). "In addition, high levels of KLK3 were seen in clusters 3 and 5 and Tregs, and KLK3 expression was detected in all T cell subsets, suggesting that the role of extracellular vesicles may accompany different stages of tumor-infiltrating T cells." (PMID 36769267, 2023). "A two-gene signature based on KLK3 and BIRC5 expression was evaluated for predicting circulating tumour cell (CTC) levels in metastatic castration-resistant PCa (mCRPC) that produced an AUC of 0.74 from a set of 29 mCRPC and 19 healthy individuals." (PMID 36033512, 2022). "From the previous study of our group, the dysregulated proteins AMBP, KLK3, LMAN2, and TTR were found dysregulated in urine and tumor tissue from PCa patients, while SECTM1 was only found in urine from PCa patients, and CDH1 and EFEMP1 were only in PCa tissue." (PMID 35454907, 2022). "If the effect of KLK3 on tumor progression is dependent on its ability to activate VEGF-C and VEGF-D, the net KLK3 effect would depend on the tumor’s expression levels of VEGF-C, VEGF-D and other proteases that are able to regulate their activity." (PMID 34948344, 2021). "These patient samples also exhibited high tumor:normal AR enrichment at the widely studied AREs near KLK2 and KLK3 suggesting higher overall AR binding." (PMID 34409300, 2021).
tumor (continued). "Herein we report a technology platformbased on novel activity-based probes (ABPs) and inhibitors enablingsimultaneous orthogonal analysis of KLK2, KLK3, and KLK14 activityin hormone-responsive PCa cell lines and tumor homogenates." (PMID 34085829, 2021). "AR can modulate the expression of TFs, biomarkers and vital tumour promoters in PrCa development, such as KLK2, KLK3, MYC, MSMB and TMPRSS2." (PMID 32397189, 2020). "Recently, exposure of enzalutamide-resistant mCRPC cells to BETi (JQ1 and OTX015) resulted in attenuation of AR target genes (FKBP5, KLK3, ERG, and MYC) and AR-v7 expression as well as decreased CRPC cell proliferation in vitro and tumor growth in vivo." (PMID 27651838, 2016). "KLK3 or prostate specific antigen (PSA) is a serine protease, which is an established tumour marker of prostatic adenocarcinoma." (PMID 10188912, 1999). "PROX1 was also highly expressed in a separate NEPC tumor cell population that was AR and KLK3 negative but positive for NEPC markers, including INSM1." (PMID 40454483, 2025). "Notably, bone cell activity inversely correlated with tumor AR activity (AR, FOXA1, HOXB13, KLK2, KLK3, NKX3-1, STEAP2, TMPRSS2) and PSA levels." (PMID 40342734, 2025). "KLK3, like other kallikrein-related proteases, possesses proteolytic activity that may contribute to ECM component degradation, a critical process for tumor cell invasion and metastasis." (PMID 40427030, 2025). "KLK3 and FOLH1 are expressed in tumours even in early disease and may be representative of disease burden." (PMID 39840448, 2025). "Moreover, the examination of gene expression and violin plots demonstrated a high expression of a group of AR signature genes, including KLK3, AR, TMPRSS2, NKX3.1, and AMACR across all clusters, indicating their tumor origin." (PMID 38732035, 2024). "Similarly, after their culture with ECs, IL30-overexpressing PCs showed a dramatic upregulation of a wide range of oncogenes, which included CCND2, EGR3, IGFBP5, KLK3, PDLIM4, PTGS1 and SHBG and a few tumor suppressors, such as GPX3, FOXO1, MAX and NKX3-1." (PMID 38087324, 2023). "In contrast, in five primary tumours (i.e. PRAD), only KLK3 revealed strong H3K27ac activity." (PMID 37875732, 2023). "Moreover, elevated expression of KLK3, prostate-specific antigen (PSA) gene in T cells (AR-negative) was observed, attributed to extracellular vesicle/exosome-mediated trafficking from the tumor cells to T cells." (PMID 35669415, 2022). "Given that tumor cells predominantly express LE cell markers such as KLK2, KLK3, ACPP, and NKX3-1, clusters with high LE signatures scores could be either tumor cells or non-malignant LE cells." (PMID 35013146, 2022). "While we have previously observed lower levels of CTC KLK3 gene expression compared to primary tumours in all PDX models in non-castrated mice, KLK3 expression was similar in CTC and tumour samples from castrated mice." (PMID 35493092, 2022). "ERG+ and ERG− tumor cells and non-malignant LE cells all showed high expression of luminal markers KLK3, KLK2, and ACPP35." (PMID 35013146, 2022). "qRT-PCR of the lysate of cells captured in the microchannels indicated the presence of cells expressing AR and/or KLK3 but not necessarily that of tumor-derived PCA3 and PSMA genes." (PMID 34771706, 2021). "However, VEGF-D loses most of its lymphangiogenic signaling capacity upon cleavage by KLK3 or CTSD, while maintaining most of its angiogenic signaling potential, thus, resembling tumor-derived VEGF-D." (PMID 34948344, 2021). "This might be explained by the hypothesis that KLK3 reflects CTC’s, since most of the CTC’s are KLK3 positive while PSA is most likely secreted by tumor masses in the body." (PMID 34944897, 2021). "KLK3, AZGP1 and PIP are AR regulated and reflect tumor AR activity." (PMID 34736512, 2021). "This study shows that, at least in principle, KLK3 could contribute to the activation of tumor-derived VEGF-C or VEGF-D and thus to a (lymph)angiogenic tumor phenotype." (PMID 31099754, 2019).
tumor (continued). "Significantly downregulated genes in NHT tumours (DESeq comparison; Benjamini-Hochberg P <0.05) were typically androgen responsive (for example, TMPRSS2, KLK3, BMPR1B, TPD52) or steroidogenesis-related (for example, DHCR24, SCD), consistent with a reduction in androgen receptor activity." (PMID 25155515, 2014). "For patients treated by focused radiation, the cancer markers but not ACPP, AZGP1, KLK3 would be lost if the tumor is successfully ablated." (PMID 23029164, 2012). "In our analysis, the androgen regulated genes enriched in tumor with no deletion of PTEN include genes expressed in normal prostate luminal epithelium such as KLK3 (PSA), TMPRSS2, and NKX3-1." (PMID 23171135, 2012). "While it is difficult to make direct comparisons between this study and others that used LCM to examine altered expression in tumor vs. normal epithelia, we and others observed genes elevated in prostate cancer epithelial cells including kallikrein proteins 2 (KLK2), and 3 (KLK3, or PSA)." (PMID 20426842, 2010). "Notably, within these early-passage organoids we identified a population fitting our profiling of ERG+ tumor cells, expressing a high level of LE cell markers (KLK3, KLK2, and ACPP) and tumor markers (PCA3, TRPM8, and ERG), which we annotated as putative tumor cells." (PMID 35013146, 2022). "Identification of seven genes (MYLK, KLK2, KLK3, HAN11, LTF, CSRP1, TGM4) which have their connectivity altered between normal/tumoral conditions may provide novel insights into specific targets against tumor progression." (PMID 19055846, 2008). "Besides PSA, a protease in the Kallikrein family (KLK3) regulated by androgen signaling, matrix metalloproteases (MMPs) are a family of proteolytic enzymes that are known to degrade extracellular matrix (ECM) and support tumor proliferation and growth as well as migration, and metastasis." (PMID 35669415, 2022).